MET (MET proto-oncogene, receptor tyrosine kinase)
Diseases named in the same sentence as MET in open-access papers (continued):
Sharing a sentence is not in itself a finding about the gene and the disease.
pancreatic cancer (continued). "Hence, we identified the expression of c-MET in pancreatic cancer and then investigated whether Crizotinib inhibited the phosphorylation of c-MET in pancreatic cancer cells." (PMID 25193856, 2014). "Under the effect of ceRNA regulation, cascades ADAM12, MET, QKI, SEC23A, and ZEB2 were reported as PDAC disease signatures that significantly impacted the survival rates of pancreatic cancer patients." (PMID 40728965, 2025). "Recent studies have explored innovative approaches targeting the MET pathway, including the use of chimeric antigen receptor macrophages (CAR-M-c-MET) to inhibit pancreatic cancer progression." (PMID 40565031, 2025). "The capacity of MACC1 to upregulate c-MET expression transcriptionally has been shown in CRC, ovarian cancer (OC), pancreatic cancer (PDAC) and osteosarcoma." (PMID 39580452, 2024). "Clinically, elevated expression of MET proto-oncogene, receptor tyrosine kinase (MET) and AXL receptor tyrosine kinase (AXL) or their ligands correlates with worse status in pancreatic cancer patients." (PMID 39000029, 2024). "Zhang reported that the genes MET, MUC16, and KRT7 in the model had high expression levels in pancreatic tumor tissues as validated by RT-qPCR." (PMID 39127853, 2024). "In the context of pancreatic cancer, uPA is particularly significant due to its essential function in activating the HGF/c-MET pathway." (PMID 38473413, 2024). "This is also the first study of the effect of NPS-1034, a dual inhibitor of MET and AXL, on pancreatic cancer." (PMID 39000029, 2024). "MET and AXL are important regulators of pancreatic cancer because they are receptor tyrosine kinases (RTKs) that function normally in healthy conditions." (PMID 39000029, 2024). "Based on GEPIA database, we found that mRNA expression of MET, KRT7, and MUC16 was remarkably higher in pancreatic tumour than in normal tissues." (PMID 37815881, 2023). "RT-qPCR validated that MET, MUC16, and KRT7 in the model had higher expression levels in pancreatic tumour tissues." (PMID 37815881, 2023). "Compared to pancreatic normal tissues, the expression levels of MET, KRT7, and MUC16 were remarkably higher in pancreatic tumour tissues." (PMID 37815881, 2023). "We examined the expression of ITGA2, MET, E-cadherin, PD-L1, CD4, and CD8 proteins in 62 pancreatic cancer tissue samples using multi-tissue immunofluorescence and immunohistochemistry techniques." (PMID 37881431, 2023). "By analysing the TCGA database, we found that the expression of PCDH1 was positively correlated with CCND1, CCNE2, VEGFA, MET, CD44 and CD133 expression in pancreatic cancer tissues." (PMID 35864095, 2022). "Recently, our team reported that circBFAR promotes the progression of PDAC via the miR-34b-5p/MET/Akt axis and that circNFIB1 inhibits lymphangiogenesis and lymphatic metastasis via the miR-486-5p/PIK3R1/VEGF-C axis in pancreatic cancer." (PMID 35189958, 2022). "Mechanistically, circBFAR binds to miR-34b-5p and decreases MET expression, thereby activating the MET/PI3K/Akt signaling pathway and promoting the progression of pancreatic cancer cells." (PMID 36467402, 2022). "According to the previous study, FYN, LRSAM1, and SEMA6C serve as poor prognostic biomarkers in pancreatic cancer, whereas ERAP2, MET, IL20RB, and CXCL11 indicate improvements." (PMID 36428747, 2022). "Overexpressed pancreatic cancer receptors include SLC2A1, MET, IL1RAP, NPR3, GABRP, SLC6A6, and TMPRSS4." (PMID 35359382, 2022). "Out of 11 ITGA3, MET, FNDC3B, PPP1R14B and KIAA0513, including PLAU, were previously reported as individual prognostic markers in the pancreatic cancer TCGA-PAAD cohort." (PMID 36591282, 2022). "The L5 proteins of 3 serotypes of adenovirus HAdV2, HAdV3, and HAdV5 are docked with the seven highly expressed pancreatic cancer receptors SLC2A1, MET, IL1RAP, NPR3, GABRP, SLC6A6, and TMPRSS4." (PMID 35359382, 2022).
pancreatic cancer (continued). "Initially, we investigated the role of two well characterized RTKs, EGFR and MET, in immune “hot” (CD8 + T-cell enriched) and “cold” (CD8 + T-cell decreased) pancreatic cancers." (PMID 34479614, 2021). "Expression analysis further revealed that CDK1, DSC2, ERO1A, MET, PYGL, and SLC35A3 were highly expressed in pancreatic cancer while CHST12 was highly expressed in normal pancreatic tissues." (PMID 33912561, 2021). "Seven GRGs: CDK1, DSC2, MET, PYGL, CHST12, ERO1A, and SLC35A3 were selected to construct the prognostic model related to the overall survival rate of patients with pancreatic cancer." (PMID 33912561, 2021). "We identified three key genes (MET, OAS1, and OASL) that were all up-regulated in pancreatic cancer and indicated an unfavorable prognosis." (PMID 33869254, 2021). "To unveil the signaling pathways sustaining stroma modulation orchestrated by MET activation in the tumor, we analyzed the gene expression profile in pancreatic cancer cells stimulated with HGF and treated with HGF/MET inhibitors." (PMID 34298732, 2021). "CDK1, DSC2, ERO1A, MET, PYGL, and SLC35A3 were highly expressed while CHST12 was decreased in pancreatic cancer." (PMID 33912561, 2021). "HGF/MET signaling promotes CSC properties by inducing YAP nuclear translocation and HIF-1α stabilization in pancreas cancer." (PMID 34439392, 2021). "To this end, we compared data obtained by large-scale analysis of gene expression in pancreatic cancer cells grown in the presence of HGF versus cells grown in the presence of HGF and treated with specific inhibitors of HGF/MET signaling." (PMID 34298732, 2021). "To understand the role of c-MET in PDAC, we used qRT-PCR and western blotting to evaluate the c-MET expression in a normal pancreatic duct epithelial cell line (HPNE) and five pancreatic cancer cell lines." (PMID 33816276, 2021). "The expression of MET, OAS1, and OASL in pancreatic cancer was verified in the GSE15471 and GSE62452 datasets." (PMID 33869254, 2021). "The levels of c-MET are increased in pancreatic carcinoma where c-MET signaling induces growth and invasion and some authors have reported c-MET as a stem cell marker in pancreatic tissue." (PMID 33637083, 2021). "Recent studies have also demonstrated that PSCs facilitate perineural invasion of pancreatic cancer and this process is mediated via the HGF/c-MET pathway." (PMID 33271944, 2020). "Apart from these classes of MET inhibitors, anti-MET antibodies (emibetuzumab (LY2875358) and onartuzumab (MetMab)) have also been successfully applied in preclinical models of pancreatic cancer." (PMID 33271944, 2020). "The current review discusses the role of the MET/HGF axis in tumour progression and dissemination of pancreatic cancer." (PMID 33271944, 2020). "Compared with PCs and iPCs, the gene expression levels of some pancreatic cancer markers (epithelial cell adhesion molecule (EpCAM), CD44, CD133, and c-MET) were significantly increased in KiPCs." (PMID 33233448, 2020). "Similar observations were made in pancreatic cancer wherein HGF was found to be secreted predominantly by PSCs and the receptor c-MET was expressed by cancer cells and endothelial cells." (PMID 33271944, 2020). "BMS777607 and PHA665752 inhibited pancreatic cancer cell viability and migration, and promoted apoptosis by inhibiting RON and MET phosphorylation and further inhibiting the downstream signaling pathways in vitro." (PMID 31867280, 2019). "Increased RON and MET expression by pancreatic cancer cells is a suitable target for anti-RON and anti-MET drugs in future cancer therapy." (PMID 31867280, 2019). "Of the 227 pancreatic cancer samples, 33% had RON overexpression (3+), 41% had MET overexpression (3+), and 15.4% had RON and MET co-overexpression." (PMID 31867280, 2019).
pancreatic cancer (continued). "The pancreatic cancer samples had significantly higher proportions of positive RON expression (195 of 227 patients, 85.9%) and MET expression (207 of 227 patients, 91.2%) compared with the normal/benign pancreatic tissue samples (5 of 20 patients, 25%)." (PMID 31867280, 2019). "Here, we used a panel of pancreatic cancer cell lines expressing different levels of RON and MET as the model." (PMID 31867280, 2019). "In 227 pancreatic cancer samples, 33% had RON overexpression, 41% had MET overexpression, and 15.4% had RON and MET co-overexpression." (PMID 31867280, 2019). "On the other hand, cabozantinib overcomes gemcitabine resistance of pancreatic cancer cells by inducing apoptosis and suppressing total c-MET, the phosphorylated c-MET and reprogramming transcription factor SOX2." (PMID 30360560, 2018). "Crizotinib, a c-MET/ALK inhibitor, shows antitumor activity in pancreatic cancer cells via suppressing growth and inducing apoptosis." (PMID 30360560, 2018). "A major factor regulating desmoplasia and subsequently promoting chemoresistance in pancreatic cancer is hepatocyte growth factor (HGF), the sole ligand for c-MET (mesenchymal-epithelial transition), an epithelial tyrosine kinase receptor." (PMID 26404380, 2015). "Combining promising c-MET and HGF antagonists along with strategic utilization of current treatment regimens leave the pancreatic cancer community with an expectant outlook for the future of medical intervention." (PMID 26404380, 2015). "In pancreatic cancer, c-MET was overexpressed up to 80% of pancreatic ductal adenocarcinoma cases, and c-MET alterations were shown to be a strong indicator for increased recurrence rates and overall poor survival for pancreatic ductal adenocarcinoma patient." (PMID 25193856, 2014). "Another study identified c-MET-, CD44-, and α6β4-receptors as mediators of a tumor matrix triggered increase in migratory potential of pancreatic tumor cells." (PMID 24213498, 2012). "Immunohistochemical results showed that among the 8 CRGs: CEP55, FAM111B, MRPL3, MET, and KNSTRN had higher protein expression in pancreatic cancer tissues, while on the contrary, the protein expression of DHX30 in normal pancreas was significantly higher than that in pancreatic cancer tissues." (PMID 40677006, 2025). "The comparative toxicogenomics database was used to search for drug molecules that could target DSG3, MET, and PLAU in pancreatic tumors, obtaining 4, 26, and 39 drug molecules, respectively." (PMID 39513120, 2024). "Furthermore, single-cell analysis revealed that MET, MUC16, and KRT7 were mainly expressed in the microenvironment of pancreatic cancer cells." (PMID 39127853, 2024). "Additionally, amatuximab treatment downregulated cancer stem cell markers, such as CD44, c-MET, and ALDH1 in pancreatic cancer cells." (PMID 35326701, 2022). "Therefore, G-6 inhibited the MET/PTEN/TGF-β pathway, mediating these currents contributions to the anti-tumor activity, and showed that G-6 is a promising anti-pancreatic cancer agent candidate potently in vitro." (PMID 36364317, 2022). "In addition to inhibited c-MET at the pharmacological level, two stable c-MET knockdown pancreatic cancer cell clones (c-MET shRNA2 and shRNA3) with higher silencing efficiency were selected for the subsequent experiments." (PMID 35693705, 2022). "Additionally, knockdown of c-MET reduced GSH content and increased MDA and lipid ROS production in activated PSC coculture and HGF-treated pancreatic cancer cells in the presence of ferroptosis inducers." (PMID 35693705, 2022). "Specifically, we identified three RTKs, MET, EPHB6, and RYK, which are associated with a poor prognosis regardless of the immune status in patients with pancreatic cancer." (PMID 34479614, 2021). "Collectively, we identified three immune-related prognostic genes MET, OAS1, and OASL, which could be promising therapeutic targets as well as prognostic markers for pancreatic cancer." (PMID 33869254, 2021).
pancreatic cancer (continued). "We previously demonstrated that the combination of a MET-targeting antibody (MvDN30) with an HGF-sequestering protein (DecoyMETK842E) strongly inhibits the HGF/MET axis in HPAF-II cells, resulting in a dramatic reduction in the ability of pancreatic cancer cells to metastasize to the lungs." (PMID 34298732, 2021). "Elevated MET and PD-L1 expressions were closely associated with lymph node metastasis, tumor TNM stage, and overall survival in pancreatic cancer." (PMID 34479614, 2021). "The MET/HGF axis is involved in the complex crosstalk between tumor and stroma, especially in the interaction between cancer cells and activated PSCs, thereby favors the progression and metastasis of pancreatic cancer." (PMID 33008376, 2020). "Simultaneous inhibition of HGF and c-MET combined with gemcitabine is more effective in reduction of tumor volume in an orthotopic model of pancreatic cancer than chemotherapy alone, indicating a critical role of the HGF/c-MET pathway in PSC–cancer cell interactions." (PMID 32116785, 2020). "Our pancreatic cancer treatment strategy included chemotherapy and HGF/c-MET inhibition." (PMID 32203220, 2020). "Many patients with pancreatic cancer with gemcitabine-resistance might benefit from a combination of RON and/or MET inhibitors." (PMID 31867280, 2019). "We used four small-molecule TKIs (BMS777607, PHA665752, INCB28060, Tivantinib) to explore the function of RON and MET in pancreatic cancer cells and whether RON and MET could serve as new targets for future treatment of pancreatic cancer." (PMID 31867280, 2019). "RON and MET staining was detected in the cell membrane and cytoplasm in cancerous and non-cancerous cells in patients with pancreatic cancer." (PMID 31867280, 2019). "Here, the lack of inhibitory effect by the MET-targeting TKIs was probably related to dosage, drug resistance, and pancreatic cancer cells being highly dependent RON signaling." (PMID 31867280, 2019). "At present, the relationship between pancreatic cancer and miRNAs-HGF/c-MET is being explored." (PMID 30360560, 2018). "Recent evidence with another c-MET inhibitor, INC280, demonstrated reduced motility of pancreatic cancer cells with a 30% lymph node involvement in the treatment group when compared to 60% involvement in the control group, suggesting potential suppression of metastasis." (PMID 26404380, 2015). "A recent study demonstrated Crizotinib exhibits anti-tumor activity by targeting ALK but not c-MET in pancreatic cancer." (PMID 25909285, 2015). "c-MET and CD44 are co-expressed in a number of cancers, such as pancreatic cancer and CRC." (PMID 24823486, 2014). "When pancreatic cancer cells were treated with Crizotinib in a dose-dependent manner, it did not inhibit the expression of both p-c-MET and c-MET." (PMID 25193856, 2014). "In conclusion, we demonstrate that Crizotinib suppresses tumor growth and angiogenesis and induces apoptosis by downregulating the ALK signaling pathway, and not c-MET in pancreatic cancer." (PMID 25193856, 2014). "Our present study revealed that Crizotinib induced apoptosis and inhibited cell growth or angiogenesis via inhibition of ALK signaling, not c-MET signaling in pancreatic cancer." (PMID 25193856, 2014). "This was further corroborated in pancreatic cancer, where the c-MET inhibitor JNJ-38877605 did not prevent direct protein–protein interaction of MACC1 with the EMT-marker SNAI1, resulting in the upregulation of fibronectin 1 (FN1) and a repression of E-cadherin." (PMID 39580452, 2024). "The lack of MET signaling could impact the ‘non-cell-autonomous’ functions required during pancreatic cancer establishment and progression, a role that could not be assessed by our in vitro analyses." (PMID 37345079, 2023).
pancreatic cancer (continued). "On the other hand, DYRK1A was highly expressed in lung and pancreatic cancer cells, and that its protein level was positively correlated with that of STAT3, c-MET and EGFR as it was found that DYRK1A siRNA could suppress the levels of EGFR and MET receptor tyrosine kinases." (PMID 36012629, 2022). "However, based on our published work with the early model of pancreatic cancer, and on the current in vitro data, it is likely that dual inhibition of HGF and c-MET can block/prevent the occurrence of new metastases, but has little effect on established metastasis." (PMID 32203220, 2020). "Thus, we submit that a therapeutic strategy involving HGF/c-MET inhibition with or without chemotherapy, is eminently ready to be taken to clinical trials for pancreatic cancer in both neoadjuvant and adjuvant scenarios." (PMID 33271944, 2020). "While present knowledge of HGF/c-MET has supported clinical trials targeting various aspects of the biological mechanism, more mature studies addressing side effects and clinical outcomes specific to pancreatic cancer are lacking." (PMID 26404380, 2015). "In the study, with regard to the mechanism of action, Crizotinib did not inhibit c-MET expression on pancreatic cancer cells; instead, it specifically inhibited the activity of ALK, which was identified to be highly expressed on various pancreatic cancer cells and tissues in our study." (PMID 25193856, 2014). "However, in this study, Crizotinib did not inhibit the phosphorylation of c-MET in pancreatic cancer cells." (PMID 25193856, 2014). "For the first time, we report that Crizotinib inhibited ALK signaling pathway and not c-MET, which may lead to the induction of apoptosis along with the inhibition of cell growth and angiogenesis in pancreatic cancer." (PMID 25193856, 2014). "It seems because Crizotinib did not function in pancreatic cancer with overexpressed c-MET." (PMID 25193856, 2014). "Hence, the dual inhibition of MET and AXL could be promising for pancreatic cancer treatment." (PMID 39000029, 2024). "Thus, MET, OAS1, and OASL could be potential therapeutic markers in pancreatic cancer." (PMID 33869254, 2021). "There are also some studies showed that elevated MET expression is a strong and independent risk factors of poor patient survival compared to RON, and the MET and RON co-expression does not appear to reflect a synergistic mechanism of reducing pancreatic cancer patient survival times." (PMID 31867280, 2019). "However, Crizotinib did not inhibit the expression of p-c-MET in pancreatic cancer cells." (PMID 25193856, 2014). "However, Qian and colleagues have demonstrated in vitro that patient tumour derived fibroblasts expressing HGF could initiate an apparent invasion-stimulating response in pancreatic cancer cells with high expression of c-MET but not in cells with low expression of c-MET." (PMID 33271944, 2020). "Although relevance between the expression of ALK and ALK gene alteration in pancreatic cancer remains to be further investigated, Crizotinib obviously showed an anticancer effect via target inhibition of ALK, and not c-MET." (PMID 25193856, 2014). "However, despite the important roles that MET and AXL play in the progression of pancreatic cancer, there has been no research on NPS-1034 and pancreatic cancer." (PMID 39000029, 2024). "Again, such explicit evidence as is seen with prostate cancer is lacking in pancreatic tumor research, and whether the acidic environment can activate the HGF-c-MET pathway needs further investigation." (PMID 26404380, 2015).